ENSG00000258728 (novel protein (GALT-IL11RA readthrough))
Gene: Protein-coding gene on chromosome 9 (34,646,631 to 34,661,886, forward strand). Ensembl gene ENSG00000258728.
Genetic constraint (gnomAD): Loss-of-function variants: 23 observed, 38.27 expected, observed/expected ratio (o/e) 0.6, 90% interval 0.43 to 0.85. Missense variants: 316 observed, 373.21 expected, observed/expected ratio (o/e) 0.85, 90% interval 0.77 to 0.93. Synonymous variants: 124 observed, 147.4 expected, observed/expected ratio (o/e) 0.84, 90% interval 0.73 to 0.98.